RNA5SP194 (RNA, 5S ribosomal pseudogene 194)
Synonyms: RN5S194
Gene: Ribosomal RNA gene on chromosome 5 (139,012,329 to 139,012,441, forward strand). Ensembl gene ENSG00000201532.
Homologues: Orthologues: chimpanzee 5S_rRNA (99% identical). Paralogues in human: RNA5S1 (78% identical), RNA5S10 (78% identical), RNA5S11 (78% identical), RNA5S12 (78% identical), RNA5S13 (78% identical), RNA5S14 (78% identical), RNA5S15 (78% identical), RNA5S16 (78% identical), RNA5S17 (78% identical), RNA5S2 (78% identical), RNA5S3 (78% identical), RNA5S4 (78% identical), and 26 more.